LAMP1 (lysosome associated membrane protein 1)
Description:
Lysosomal membrane glycoprotein which plays an important role in lysosome biogenesis, lysosomal pH regulation, autophagy and cholesterol homeostasis. Acts as an important regulator of lysosomal lumen pH regulation by acting as a direct inhibitor of the proton channel TMEM175, facilitating lysosomal acidification for optimal hydrolase activity. Also plays an important role in NK-cells cytotoxicity. Mechanistically, participates in cytotoxic granule movement to the cell surface and perforin trafficking to the lytic granule. In addition, protects NK-cells from degranulation-associated damage induced by their own cytotoxic granule content. Presents carbohydrate ligands to selectins. (Microbial infection) Acts as a receptor for Lassa virus glycoprotein. Also promotes fusion of the virus with host membrane in less acidic endosomes. (Microbial infection) Supports the FURIN-mediated cleavage of mumps virus fusion protein F by interacting with both FURIN and the unprocessed form but not the processed form of the viral protein F.
Synonyms: CD107a; LAMPA; LGP120
Tractability: Small molecule: a structure with a bound ligand is known. Antibody: UniProt places it where antibodies can reach, with high confidence; its Gene Ontology location is reachable by antibodies, with high confidence; UniProt predicts a signal peptide or a membrane-spanning region. PROTAC: ubiquitination databases record sites on it; its protein half-life has been measured.
Gene: Protein-coding gene on chromosome 13 (113,297,088 to 113,323,674, forward strand). Ensembl gene ENSG00000185896.
Subcellular location: Lysosome membrane; Endosome membrane; Late endosome membrane; Cell membrane; Cytolytic granule membrane
Pathways (Reactome):
Immune System: Neutrophil degranulation
Gene Ontology:
Molecular function: enzyme binding; ion channel inhibitor activity; protein binding; protein domain specific binding
Biological process: establishment of protein localization to organelle; Golgi to lysosome transport; granzyme-mediated programmed cell death signaling pathway; lysosomal lumen acidification; positive regulation of natural killer cell degranulation; positive regulation of natural killer cell mediated cytotoxicity; regulation of organelle transport along microtubule; protein stabilization
Cellular component: cytolytic granule membrane; cytoplasm; endosome membrane; extracellular exosome; late endosome; late endosome membrane; lysosomal membrane; lysosome; membrane; perinuclear region of cytoplasm; plasma membrane; azurophil granule membrane; ficolin-1-rich granule membrane; autolysosome; autophagosome membrane; cell surface; cytolytic granule; cytosol; endosome; external side of plasma membrane; melanosome; multivesicular body; phagocytic vesicle; phagolysosome membrane; sarcolemma; and 2 more
Genetic constraint (gnomAD): Loss-of-function variants: 6 observed, 35.05 expected, observed/expected ratio (o/e) 0.17, 90% interval 0.093 to 0.34. The upper end of that interval is the gene's LOEUF score, 0.34, which puts it in group 1 of 6, group 1 being the genes least tolerant of losing a copy. Missense variants: 510 observed, 547.29 expected, observed/expected ratio (o/e) 0.93, 90% interval 0.87 to 1. Synonymous variants: 220 observed, 220.31 expected, observed/expected ratio (o/e) 1, 90% interval 0.89 to 1.12.
Homologues: Orthologues: chimpanzee LAMP1 (94% identical), macaque LAMP1 (87% identical), dog LAMP1 (80% identical), rabbit LAMP1 (75% identical), pig LAMP1 (71% identical), guinea pig LAMP1 (70% identical), mouse Lamp1 (66% identical), rat Lamp1 (65% identical), tropical clawed frog lamp1 (43% identical). Paralogues in human: LAMP2 (34% identical), CD68 (22% identical), LAMP5 (14% identical).
Diseases named in the same sentence as LAMP1 in open-access papers:
LAMP1 is named in the same sentence as 278 diseases in open-access papers, as found by Europe PMC text mining. Sharing a sentence is not in itself a finding about the gene and the disease. The quoted sentences say what the papers report.
melanoma (60 papers, 2009 to 2026). A malignant, usually aggressive tumor composed of atypical, neoplastic melanocytes. "Subsequent investigations have demonstrated that LAMP1 interacts with galectin-3 on the lung through polyLacNAc, which is implicated in melanoma lung metastasis." (PMID 39669571, 2024). "Galectin-3 has previously been reported to increase secretion of MMP-1 and −9 in melanoma cells by binding to lysosome-associated membrane protein-1 (LAMP1)." (PMID 37055381, 2023). "Lysosome-associated membrane protein-1 (LAMP1), also known CD107a, is a surface protein that is expressed on melanoma-macrophage hybrid cells and increases their invasion and metastatic potential." (PMID 34207884, 2021). "In a single-arm phase II clinical study (NCT01302496), patients with stage III/IV malignant melanoma were treated with DCs, electroporated with TriMix, and mixed with multiple LAMP-1-fused melanoma-associated tumor mRNAs (TriMixDC-MEL), along with ipilimumab (IPI; CTLA-4 inhibitor) mAb." (PMID 37681880, 2023). "The mRNA encoding the human melanoma-associated antigen recognized by T cells 1 (MART1), a specific tumor antigen, mRNA encoding Lysosome Associated Membrane Protein-1 (LAMP1), and Bax-mRNA have been used for immunization of the mice model of melanoma using different LNP." (PMID 35701851, 2022). "In the context of disease, it has been reported that melanoma, carcinoma, and fibrosarcoma cells exhibit abnormal localization of LAMP1 on their plasma membranes, possibly as part of the repair of the damaged cell surface." (PMID 40545776, 2025). "An increase in the LAMP1 expression has also been previously reported on the surface of SEN from the human melanoma line SK‐MEL‐103 and in the membrane fraction of etoposide‐treated SEN." (PMID 40545776, 2025). "Utilizing shRNA to downregulate LAMP1 in B16F10 mouse melanoma cells can attenuate the induction of matrix metalloproteinase (MMP9) expression by the p38 MAPK signaling pathway activated by galectin-3 and polyN-acetyllactosamine (polyLacNAc)." (PMID 39669571, 2024). "Although LAMP1 primarily resides at the lysosomal membrane, its localization to cell surface expression was described to mediate cell-cell adhesion and favor melanoma cell invasion." (PMID 38218945, 2024). "In human metastasizing melanoma, fibrosarcoma, ovarian, and colon carcinoma cells, LAMP-1 and LAMP-2 were found to serve as GAL-1- and GAL-3-binding partners." (PMID 37898403, 2023). "No signal overlap was detected between this tagged protein and other organelle markers, including GM130 for cis-Golgi, TGN46 for trans-Golgi, LAMP1 for lysosomes, and anti-melanoma antibody for melanosomes in MelJuSo." (PMID 37958830, 2023). "According to the results of a previous study, the decreased metastasis of melanoma cells to the lung was observed by the downregulation of LAMP1 expression." (PMID 35145930, 2022). "We found that this process is exacerbated in the case of senescent melanoma cells, as revealed by the exposure of lysosomal membrane integral proteins LAMP1 and LAMP2 in their plasma membrane." (PMID 36087066, 2022). "Confocal microscopic analysis indicated that cell surface located PD‐L1 showed negligible colocalization with p62, LC3, or LAMP1 in melanoma cells under the IFN‐γ induction." (PMID 33510997, 2021). "An in vitro study using melanoma cells concluded that LAMP1 is used for regulation of carbohydrates." (PMID 31683886, 2019). "B16 cells showed a web-like tubular staining pattern of LAMP-1, similar to those observed in macrophage and dendritic cells, possibly reflecting the notion that melanocytes/melanoma are potential immunocompetent cells." (PMID 29045474, 2017). "Down-regulation of LAMP1 significantly reduced the metastatic capacity of melanoma cells." (PMID 34207884, 2021). "Lamp1 was a major carrier of polyLacNAc substituted β1,6 branched GlcNAc in melanoma cells." (PMID 32612952, 2020).
melanoma (continued). "The expression of LAMP1 has been observed on the surface of tumor cells from highly metastatic cancers, suggesting its role in the progression of lung cancer, colon cancer, and melanoma." (PMID 32101552, 2020). "Surprisingly the opposite was found for lysosomal related organelles (LAMP1 positive structures), suggesting that the melanoma cells may be using these LAMP1 positive intracellular organelles for hypericin-PDT resistance." (PMID 25076130, 2014). "To shed more light on these phenomena we investigated hypericin co-localization with endosomes, lysosomes and melanosomes (LAMP1 positive structures), in one of the melanoma cell lines (501mel) before and after PDT, using super-resolution structural illumination microscopy." (PMID 25076130, 2014). "By flow cytometry, GAL-3 was shown to bind LAMP-1 and LAMP-2 at the surface of A2058 melanoma, HT1080 fibrosarcoma, and CaCo-2 colon carcinoma cells." (PMID 37898403, 2023). "By interacting with poly-LacNAc structures on LAMP-1, GAL-3 induced the expression of MMP9 in a p38 MAPK-dependent manner, revealing a possible mechanism for melanoma cell invasion and metastasis." (PMID 37898403, 2023). "Melanoma SK‐MEL‐103 cells treated with the CDK4/6 inhibitor, palbociclib, displayed SAβGal staining and increased protein levels of the lysosomal membrane proteins LAMP1 and LAMP2." (PMID 36087066, 2022). "(C) Quantitation using Fiji of the colocalization of MFSD1-eGFP with the Golgi marker (GRASP65), early endosome marker (Rab5), late endosome marker (Rab7), and lysosome marker (LAMP1) in MC-38 colon carcinoma, B16-BL6 melanoma, LLC1 Lewis lung carcinoma, and 4T1 breast carcinoma cells." (PMID 30910009, 2019). "As example, LAMP1 (a gene with an intronic CAML discovered in MEL, GBM, LGG, and MB) is identified with melanoma metastasis to lung tissue and notable LAMP1 expression on the cell membrane of astrocytomas was recently discovered in immunohistochemistry analysis." (PMID 26246470, 2015).
COVID-19 (46 papers, 2020 to 2025). A disease caused by infection with severe acute respiratory syndrome coronavirus 2. "Notably, NK cell expression of degranulation marker CD107a (LAMP-1; lysosomal-associated membrane protein 1) in the patient with myopericarditis after COVID-19 mRNA vaccine was higher than that of recently vaccinated controls." (PMID 35251049, 2022). "However, the expression of both LC3IIB puncta and LAMP1 was more regularly distributed in PBMCs from HDs as compared to PBMCs from COVID-19." (PMID 35711451, 2022). "In PBMCs from COVID-19 and HDs, the expression of LC3IIB and LAMP1 was diffusely detectable." (PMID 35711451, 2022). "Specifically, in the COVID-19 patient’s B cells, we detected a substantial increase in the expression of CD52, CD74, CD22 and CD79B and a decrease in CXCR4, CD69, INFGR1, PTPRC and LAMP1 transcripts with respect to control-derived B cells." (PMID 34944610, 2021).
breast carcinoma (35 papers, 2009 to 2025). "The overexpression of lysosome-associated membrane protein 1 (LAMP1) has been demonstrated in different types of cancers, such as ovarian carcinoma, esophageal squamous cell carcinoma, breast cancer, and colorectal carcinoma." (PMID 35145930, 2022). "Autophagy markers, such as Beclin-1, LC3-II, lysosomal-associated membrane protein 1 (LAMP-1), and cathepsin-D, were upregulated in both breast cancer cell lines." (PMID 30654580, 2019). "The association between LAMP1 expression and clinicopathological features of breast cancer, such as histological grade and lymph node metastasis, highlighted that LAMP1 might be a prognostic marker in patients with breast cancer." (PMID 35145930, 2022). "As shown in our study, C118P induced autophagy in breast cancer cells and increased expression of the autophagy markers LAMP-1, LC3-II, and Beclin1." (PMID 37894450, 2023). "A previous study investigating the expression of LAMP1 in breast cancers exhibited a higher expression of this protein than corresponding non-cancerous tissues." (PMID 35145930, 2022). "Another investigation into the expression of LAMP1 in breast cancer revealed the correlation between LAMP1 expression levels and the histological grade of tumors." (PMID 35145930, 2022). "Data showed that LAMP1 was highly expressed in a variety of tumors, such as laryngeal cancer, ovarian cancer, and breast cancer." (PMID 33133307, 2020). "Upon silencing of FUT1 in MCF-7 and T47D breast cancer cells, we observed a striking change in the subcellular distribution patterns of LAMP-1 and 2 by immunofluorescence staining." (PMID 27560716, 2016). "We have also demonstrated that LeY antigens carried by LAMP-1 and 2 in weakly invasive breast cancer cells are significantly more abundant than those from highly invasive cancer cells." (PMID 27560716, 2016). "Furthermore, analysis using a multivariate COX regression model and Kaplan-Meier survival curves in breast cancer revealed that elevated LAMP1 expression is an independent prognostic factor affecting overall patient survival." (PMID 39669571, 2024). "Thus, this is the first report to provide evidence for the involvement of FUT1 in the topographical distribution of LAMP-1 and 2 that subsequently influences the autophagic activity and process of breast cancer cells." (PMID 27560716, 2016). "In addition, LAMP1 glycosylation exhibits tumor-specific alterations in pancreatic and breast cancers, influencing extracellular matrix interactions, drug response, and tumor heterogeneity, suggesting its potential as a biomarker and functional modulator in cancer." (PMID 41061966, 2025). "When the dormant breast cancer cells D2.OR were grown in basal membrane extract enriched with collagen I, the levels of LC3 and LAMP1 were significantly reduced." (PMID 39682261, 2024). "Interestingly, dormant breast cancer cells cultured in a basal membrane extract displayed an increased expression of autophagy markers such as microtubule-associated protein 1 A/1B-light chain 3 (MAP1LC3, known as LC3) and Lysosomal-Associated Membrane Protein 1 (LAMP1)." (PMID 39682261, 2024). "The molecular analysis of LAMP1 expression has demonstrated that LAMP1 might play a biological role in the progression and development of different cancers, such as colorectal tumors, pancreatic carcinoma, ovarian cancer, breast cancer, and esophageal squamous cell carcinoma (ESCC)." (PMID 35145930, 2022). "The cell surface expression of LAMP1 has been demonstrated to be correlated with the metastatic function of human colon carcinoma, ESCC, and breast carcinoma." (PMID 35145930, 2022). "Based on our recent observations using breast cancer model and CD4 depletion studies, CD4 T-cell activation (which results from LAMP1-antigen fusion) was found to be essential for the initial stages of CD8 T-cell activation." (PMID 35651802, 2022).
breast carcinoma (continued). "Pyrimethamine, at least in breast cancer cells, is sufficient to induce an immune-stimulatory effect by inducing tumor infiltration of CD8+ T-cells with elevated Lamp1." (PMID 33374980, 2020). "Cyclin D1Stroma increased breast cancer epithelial cell autophagy, increasing the abundance of BCN1 and LAMP1." (PMID 29137220, 2017). "In contrast, when mouse (JC) breast cancer cells were treated with quercetagetin, the immunocytochemical labelling of the autophagic proteins LAMP1 and LC3 did not increase significantly." (PMID 41268058, 2025). "We found a substantial colocalization between LAMP1, VANGL2 and p62/SQSTM1 in breast cancer cells." (PMID 26754771, 2016). "In addition, they described amplification of CUL4A (25.7%), LAMP1 (13.5%), TFDP1 (31.1%), and GAS6 (13.5%) by DNA qRT-PCR on a set of 74 human breast carcinomas." (PMID 19995430, 2009). "Breast cancer cells lacking STARD7 also showed elevated levels of LAMP1 or LAMP2, which, together with flow cytometry analyses using Lysotracker, demonstrates that STARD7 deficiency in both MCF7 and MDA‐MB231 but not in T47D cells led to an increased in lysosomal biomass, a hallmark of autophagy." (PMID 40443279, 2025). "Additionally, we observed downregulation of genes such as POLR1A, POLR1D, POLR1E, TAF1B, LAMP1, and CDKN1A in response to AQ treatment demonstrating the role of AQ in regulating RNA polymerase subunits and effect on overall gene transcription in breast cancer." (PMID 36232751, 2022). "Although LeY carried by surface LAMP-1 has been suggested to be involved in cell migration in breast cancer, no studies so far showing the correlation of FUT1-modified LAMP-1 and/or LAMP-2 with lysosomal localization and autophagic process." (PMID 27560716, 2016).
leukemia (29 papers, 2010 to 2025). A malignant (clonal) hematologic disorder, involving hematopoietic stem cells and characterized by the presence of primitive or atypical myeloid or lymphoid cells in the bone marrow and the blood. "TEVs carrying miR-23a have been shown to reduce expression of lysosomal-associated membrane protein 1 (CD107a/LAMP1), an NK cell activation marker, in leukemia and lung adenocarcinoma." (PMID 36498469, 2022). "Exosomal miR-23a derived from human lung cancer and leukemia cultured cell lines was shown to reduce NK in vitro cytotoxicity following co-incubation, likely due to reduced CD107a (LAMP-1) surface expression." (PMID 32793238, 2020). "Also, immunofluorescence of LAMP1 similarly a diffused cellular distribution of lysosomes in cell lines from leukemia (MV‐4‐11), bladder (J82), and NSCLC (H1781) cancers with FLT3, FGFR, and Her2 tyrosine kinase mutations, respectively." (PMID 32194831, 2020).
viral infection (24 papers, 2011 to 2026). "While it is possible that the Lamp1-positive endosomes represent late endosomes or lysosomes, the relevance of the association to virus infection mechanism is questionable since Rab7, which controls vesicular transport out of MVBs, does not play a role in CCHFV infection." (PMID 25233119, 2014). "Mechanically, CTSB hyperactivation and inappropriate cytoplasmic translocation increase viral infections by decreasing LAMP-1 + lysosomes, exacerbating lysosomal membrane permeabilization (LMP), and enhancing exosomal release of virions." (PMID 41277866, 2026). "The results revealed that VPS34 co-localized with LC3 and LAMP1 during viral infection, mirroring the effects observed in the RAPA-treated group, which indicated its involvement in the autophagosome-lysosome fusion stage." (PMID 41288077, 2025). "While approximately 38% colocalization between PRRSV and EEA1 was observed at 3 hpi, only 12% colocalization between PRRSV and LAMP-1 was observed at 3 h after virus infection." (PMID 40871241, 2025). "We have shown that viral infection led to the reduced expression of N-glycosylated Lamp1 on lysosomal membranes." (PMID 35533206, 2022). "Upon viral infection, fractions 4-6 maximally expressed LAMP1 indicating the presence of late endosomes, while fractions 9-11 were enriched with caveolin-1, indicating the presence of caveolae." (PMID 24147000, 2013). "RNAi assay was then performed to explore the role of Lamp1 during viral infection in R. dorsalis." (PMID 35533206, 2022). "The median expression of some genes (CTBP1, LAPTM4B, CFAP45, DSC2, LAMP1, EXOG, RPS21, and SIRPB1) was higher in bacterial compared to viral infection." (PMID 41496780, 2025). "In addition to these techniques, the development of haploid cell-based screening opened the opportunity to identify critical host factors for viral infections, as exemplified by NPC1 for filovirus infections or LAMP1 for LASV virus entry." (PMID 37880247, 2023). "At pH 4.0, where fusion is LAMP1-independent, and in the absence of cell-surface LAMP1, 25.10C could neutralize virus infection, while 36.1F could not (right)." (PMID 35613585, 2022). "Nevertheless, the mRNA levels of two other LAMP protein family members, LAMP1 and LAMP2, were not altered at any time points indicated, suggesting that LAMP3 may be specifically stimulated by viral infection." (PMID 21810281, 2011).